CHI3L1 (chitinase 3 like 1)
Diseases named in the same sentence as CHI3L1 in open-access papers (continued):
Sharing a sentence is not in itself a finding about the gene and the disease.
lung carcinoma (continued). "We determined the intracellular localization of Chi3L1 in the lung cancer cells." (PMID 32127023, 2020). "Therefore, secretory CHI3L1 plays an important role in inflammation-induced lung cancer formation and potentially serve as a biomarker for lung cancer prediction." (PMID 23613996, 2013). "This supports a concept that CHI3L1 stimulates lung cancer proliferation and growth." (PMID 23613996, 2013). "We are the first group to study CHI3L1 using multiple spontaneous lung cancer animal models." (PMID 23613996, 2013). "The novelty of this work is three folds: 1) Although it has been demonstrated that CHI3L1 is associated with human lung cancer, no study has been done in lung cancer animal models." (PMID 23613996, 2013). "Indeed, the CHI3L1 protein concentration in the serum of human patients with several types of lung cancer was significantly elevated." (PMID 23613996, 2013). "Furthermore, CHI3L1 depletion decreased LC3 puncta formation in lung cancer cell lines." (PMID 37340009, 2023). "In addition, PERK protein levels were increased by depletion of CHI3L1 in lung cancer cells." (PMID 37215572, 2023). "However, the molecular mechanism by which CHI3L1 regulates autophagy and is involved in lung cancer is unknown." (PMID 37340009, 2023). "Thus, it can be speculated that inhibition of the interaction between CHI3L1 and IL‐13Rα2 by K284 could prevent lung cancer cell metastasis and growth." (PMID 34758182, 2022). "Thus, in the present study, we investigated whether ebractenoid F inhibits lung cancer cell growth and migration, as well as whether it induces apoptosis through disruption of the CHI3L1/AKT signals." (PMID 36615523, 2022). "Additionally, CHI3L1 may link inflammation of bronchial tissue, COPD and lung cancer and provide an explanation for COPD as risk factor of lung cancer." (PMID 26425658, 2015). "Together, our data suggest that the depletion of CHI3L1 induces ER stress and UPR activation in lung cancer cells." (PMID 37215572, 2023). "The double depletion of CHI3L1 and SOD1 decreased the ER chaperone proteins (Grp78 and PDI) and PERK signaling proteins compared with the depletion of CHI3L1 in lung cancer cells and metastatic lung tumor tissues." (PMID 37215572, 2023). "Our data show that under ER stress conditions, the depletion of CHI3L1 greatly induced further ER stress and eventually activated the UPR in both normal and cancerous lung cells, but to a greater extent in lung cancer cells." (PMID 37215572, 2023). "The depletion of CHI3L1 increased the CHOP, cleaved caspase 12 levels and Bax/Bcl2 ratio in A549 lung cancer cells." (PMID 37215572, 2023).
lung carcinoma (continued). "Lung cancer growth and metastasis were also effectively controlled through STAT6-dependent M2 polarization inhibition by anti-CHI3L1 antibodies." (PMID 36615523, 2022). "However, the underlying mechanisms by which K284 acts on CHI3L1 and CHI3L1‐associated signaling in the metastases of lung cancer could not be completely elucidated." (PMID 34758182, 2022). "In our in vitro study, inhibitory effects of K284 on the binding of CHI3L1 to IL‐13Rα2 blocked JNK, AKT, and AP‐1 signaling and the expression of related genes (c‐Fos and c‐Jun) in cultured lung cancer cells." (PMID 34758182, 2022). "Our previous study revealed higher levels of CHI3L1 expression and phosphorylated AKT in tissue samples in patients with lung cancer." (PMID 36615523, 2022). "This study provides the importance of anti‐Chi3L1 antibody regulating tumor growth and metastasis through STAT6‐dependent M2 polarization inhibition in lung cancer." (PMID 34861103, 2022). "In the present study, we demonstrated the critical role of intracellular Chi3L1 in both an in vitro and in vivo system using Chi3L1 knockout mice (Chi3L1KO(−/−)) generated by CRISPR/Cas9 system, lung cancer cells, and lung tumor patient samples." (PMID 32127023, 2020). "Here, we report that secretory protein Chitinase 3-Like 1 (CHI3L1), a Stat3 downstream gene product, is a potential biomarker for lung cancer prediction in various animal tumor models and humans." (PMID 23613996, 2013). "Additionally, CHI3L1 targets IL-13Rα2, activating the PI3K/Akt pathway to increase lung cancer cell proliferation, migration, and invasion." (PMID 38177294, 2024). "Several studies have reported a strong correlation between elevated expression levels of CHI3L1 (YKL40) in the serum of patients with various cancers, including breast, gastrointestinal, liver, prostate, brain, endometrial, and lung cancers, as well as astrocytomas." (PMID 38543093, 2024). "The results showed that endogenous CHI3L1 and Grp78 interacted in both normal and cancerous lung cells; however, the interaction between CHI3L1 and Grp78 was greater in lung cancer cells compared with normal lung cells." (PMID 37215572, 2023). "Unlike in normal cells, the depletion of CHI3L1 increased ER chaperone protein levels in lung cancer cells." (PMID 37215572, 2023). "Lung cancer cells were pretreated with the AKT inhibitor 30 min before their treatment with ebractenoid F; then, the expression levels of proteins related to cell growth and apoptosis and CHI3L1 were analyzed." (PMID 36615523, 2022). "Compared with human serum samples without any cancer (normal), the CHI3L1 protein concentration was significantly elevated in human serum samples from all categories of lung cancer patients." (PMID 23613996, 2013). "Therefore, our findings suggest a novel mechanism for the induction and signaling of autophagy by CHI3L1 in lung cancer and suggest that autophagy inhibition by CHI3L1 can be a novel therapeutic application for lung cancers." (PMID 37340009, 2023). "Myc-CHI3L1 plasmid DNA was transfected in lung cancer cells with or without HCQ to determine whether CHI3L1 overexpression induces autophagy flux." (PMID 37340009, 2023). "In addition, we investigated whether CHI3L1 overexpression induced LC3 puncta formation by fluorescent staining of A549 and H460 lung cancer cells with LC3 antibodies." (PMID 37340009, 2023). "Our IF-IHC results of LLC allograft in mouse and tumor specimens from lung cancer patients demonstrated a strong expression of CHI3L1 in macrophages, CD4+ T cells and CD8+ T cells, suggesting that macrophages and T cells are an important source of CHI3L1 in tumors." (PMID 34987649, 2022). "CHI3L1 may serve as a new target for treatment of COPD/emphysema and lung cancer." (PMID 23613996, 2013).
chronic obstructive pulmonary disease (43 papers, 2009 to 2025). A chronic and progressive lung disorder characterized by the loss of elasticity of the bronchial tree and the air sacs, destruction of the air sacs wall, thickening of the bronchial wall, and mucous accumulation in the bronchial tree. "The elevated level of CHI3L1 is also observed in chronic obstructive pulmonary disease (COPD), and plays a role in the pathogenesis of cigarette smoke-induced inflammation and emphysema." (PMID 23613996, 2013).
coronary artery disease (43 papers, 2009 to 2025). "Higher Chi3l1 levels are also observed in other DM-associated cardiovascular complications, such as ischemic heart disease (IHD) and peripheral arterial disease (PAD)." (PMID 39769202, 2024). "Increased systemic expression of CHI3L1 has been known to be independently associated with the presence of coronary artery disease and can be used as a surrogate to measure disease progression." (PMID 38110934, 2023). "In clinical practices, studies demonstrated that elevated serum CHI3L1 levels were independently associated with coronary artery disease, and patients with the severity of coronary atherosclerosis had higher CHI3L1 levels." (PMID 34349665, 2021). "Studies have shown that CHI3L1 levels are associated with both the presence and the extent of coronary artery disease and predict all-cause and cardiovascular mortality." (PMID 28319050, 2017). "A significant positive correlation was reported between CHI3L1 levels and the progression or severity of coronary artery disease." (PMID 38177294, 2024). "For instance, the most significantly upregulated gene in the spinal cord, CHI3L1, is related to a variety of inflammatory disorders and coronary artery disease." (PMID 34349785, 2021). "Recent data show that CHI3L1 is elevated in patients with coronary artery disease, and that disease progression corresponds with augmented CHI3L1 levels." (PMID 25358394, 2014). "Both YKL-40 levels and CHI3L1 gene variants have been associated with the risk of stroke, while only the former was found associated with coronary artery disease." (PMID 25486056, 2014). "We investigated the association between single nucleotide polymorphisms (SNPs) of CHI3L1, serum YKL-40 levels and all-cause and cardiovascular mortality and first-time incidence of myocardial infarction, ischemic heart disease (IHD) and stroke." (PMID 22937056, 2012). "Reportedly, Chi3l1 can predict coronary artery disease (CAD) in asymptomatic patients with T2DM, and the single nucleotide polymorphism (SNP) rs946263 of the Chi3l1 gene is correlated with both insulin resistance and the severity of CAD in T2DM patients." (PMID 39769202, 2024). "The glycoprotein YKL-40, also named chitinase-3-like-1 (CHI3L1), is an inflammatory marker, found to be elevated in conditions characterized by low-grade inflammation, such as myocardial infarction, and stable coronary artery disease, type 2 diabetes, and morbid obesity." (PMID 24303210, 2013). "Studies on patients with acute myocardial infarction, stable coronary artery disease, atrial fibrillation and CHF have demonstrated elevated levels of CHI3L1 compared with healthy controls." (PMID 31936828, 2020). "As an example, one study investigated the influence of statin treatment on CHI3L1 and high-sensitivity CRP levels in patients with stable ischemic heart disease (IHD)." (PMID 30311184, 2018). "We also performed ELISA to investigate the corresponding proteins levels of selected genes and showed that serum levels of SPP1, CD36, ATP6V0D2, CHI3L1, MYH11, and BDNF were differentially expressed in patients with coronary heart disease compared with healthy subjects." (PMID 31682178, 2019).
ovarian carcinoma (40 papers, 2007 to 2025). A malignant neoplasm originating from the surface ovarian epithelium. "CHI3L1 is implicated in promoting ovarian cancer cell proliferation, invasion, migration, tumor angiogenesis, chemoresistance, and has significant potential as a theranostic target." (PMID 40836974, 2024). "Several studies have indicated that serum or plasma levels of CHI3L1(YKL40) can be used to assess treatment response and prognosis in ovarian cancer patients, in which a higher expression of CHI3L1(YKL40) was associated with poorer outcomes." (PMID 38543093, 2024). "Elevated CHI3L1 levels were associated with unfavourable prognoses and reduced survival rates in breast, colon and ovarian cancer patients." (PMID 37902124, 2023). "MiR-103a-3p significantly influences ovarian cancer dynamics by suppressing CHI3L1, effectively inhibiting proliferation and angiogenesis." (PMID 38793064, 2024). "CHI3L1 secretion by cancer stem-like cells leads to the inhibition of drug-induced apoptosis in ovarian cancer." (PMID 37958973, 2023). "Several studies have shown that CHI3L1 can promote the stem-like properties of ovarian cancer cells, leading to poor prognosis." (PMID 37838657, 2023). "Of special attention is the description of the expression levels of genes such as POSTN, CHI3L1, CAV-1, IRS1, DCN, which according to literature data are associated with diseases such as POI, PCOS, and ovarian cancer." (PMID 34827207, 2021). "Based on the CHI3L1 expression in ovarian cancer tissue, appropriate candidates can be selected to receive combinations of paclitaxel-platinum chemotherapy and other novel anti-apoptotic agents, especially Mcl-1." (PMID 26452028, 2015). "Further clinical trials are needed to prove the utility of CHI3L1 in managing patients with ovarian cancer." (PMID 26452028, 2015). "Our in vitro experiments also show that CHI3L1 can promote ovarian cancer cell resistance to paclitaxel by up-regulating Mcl-1." (PMID 26452028, 2015). "In vitro studies showed that CHI3L1 up-regulated the expression of anti-apoptotic Mcl-1 protein and hampered paclitaxel-induced apoptosis of ovarian cancer cells." (PMID 26452028, 2015). "We found that CHI3L1 interfered with the paclitaxel-induced apoptosis of human ovarian cancer cells by up-regulating the anti-apoptotic Mcl-1 molecule." (PMID 26452028, 2015). "Our results indicate that CHI3L1 could up-regulate the expression of Mcl-1 in favor of anti-apoptotic pathways to hamper the apoptosis induced by chemotherapeutic drugs in ovarian cancer cells." (PMID 26452028, 2015). "The results of this study may clarify the role of CHI3L1 in ovarian cancer and elucidate whether CHI3L1 is a potential biomarker of chemoresponse and a potential target for the treatment of patients with EOC." (PMID 26452028, 2015). "Additionally, CHI3L1(YKL40) has a significant impact on the generation of ovarian cancer stem cells by activating the Akt and ERK signaling pathways to promote the expression of β-catenin and SOX2, thus endowing ovarian cancer cells with characteristics of cancer stem cells." (PMID 38543093, 2024). "In addition, several proteins which previously have been shown to be elevated in the serum of ovarian cancer patients such as Chitinase-3-like protein 1(CHI3L1) [Rsc = 4.5], Haptoglobin (HP) [Rsc = 4.0] and Alpha-2-macroglobulin (A2M) [Rsc = 2.5] were elevated in CR." (PMID 27470985, 2016). "Therefore, we further investigated whether CHI3L1 plays a role in the chemoresistance of ovarian carcinoma." (PMID 26452028, 2015). "Translational experiments have revealed that CHI3L1(YKL40) promotes the expression of the Mcl-1 protein, inhibiting the apoptotic effect induced by paclitaxel in ovarian cancer cells and conferring resistance to paclitaxel." (PMID 38543093, 2024). "However, the role of CHI3L1 in ovarian cancer and chemoresistance is currently unknown." (PMID 26452028, 2015).
ovarian carcinoma (continued). "Other investigators have reported that CHI3L1 (also known as YKL-40) is an important biomarker for breast and ovarian cancer." (PMID 20003342, 2009). "In our study, we used real-time quantitative PCR (qRT-PCR) to measure the quantitative expression of CHI3L1 in ovarian cancer tissues without the influence of other malignancies or medical diseases." (PMID 26452028, 2015). "Therefore, we used qRT-PCR in this study to quantitatively measure CHI3L1 expression in ovarian cancer tissues without the influence of other malignancies or medical diseases." (PMID 26452028, 2015). "However, the biological function of CHI3L1 in ovarian cancer had not been explored." (PMID 26452028, 2015).
colon cancer (38 papers, 2007 to 2025). "IDGFs are conserved proteins homologous to human chitinase-like proteins such as CHI3L1/YKL-40 which are implicated in tissue regeneration as well as cancers including colon cancer and non-small cell lung cancer." (PMID 33370287, 2020). "High levels of CHI3L1 are associated with poor prognosis and accelerate the proliferation of colon cancer cells and increase the sensitivity to cetuximab." (PMID 31536166, 2020). "In conclusion, high levels of CHI3L1 are associated with poor prognosis in colon cancer patients." (PMID 31536166, 2020). "CHI3L1 has been proven to be involved in asthma, lung fibrosis, atherosclerosis, Alzheimer's disease, and various cancers such as colon cancer, glioblastoma, prostate cancer, and cervical cancer." (PMID 40821115, 2025). "In an in situ colon cancer model, treatment with CHI3L1 antibodies significantly reduced the growth of primary tumors and suppressed tumor metastasis to the liver." (PMID 38003338, 2023). "We developed polyclonal neutralizing-CHI3L1 antibodies (nCHI3L1 Abs) to validate the therapeutic efficacy in orthotopic lung, pancreas and colon cancer allograft models." (PMID 34987649, 2022). "In this study, CHI3L1 was overexpressed in colon cancer cells by lentiviral technology, and the sensitivity of colon cancer cells to cetuximab was evaluated." (PMID 31536166, 2020). "The results showed that the sensitivity of cells to cetuximab increased with the increase of CHI3L1 in the concentration range of 31.25‐250 ng/mL, indicating that high level of CHI3L1 will increase the sensitivity of colon cancer cells to cetuximab." (PMID 31536166, 2020). "In this study, qPCR was used to detect the expression level of CHI3L1 in colon cancer cells, and the highest expression level was found in HCT116 and SW620 cells, which provided a basis for subsequent rectal cancer cell screening." (PMID 31536166, 2020). "In this study, we investigated the mechanism of CHI3L1 in promoting colon cancer cell proliferation and its correlation with the sensitivity of cetuximab." (PMID 31536166, 2020). "The effect of cetuximab on the cell cycle of colon cancer cells before and after CHI3L1 overexpression was detected by flow cytometry." (PMID 31536166, 2020). "About 31.25, 62.5, 125, 250, and 500 ng/mL of exogenous CHI3L1 protein were added to the two colon cancer cells, and the sensitivity of which to cetuximab was detected." (PMID 31536166, 2020). "The expression of CHI3L1 in colon cancer and adjacent tissues were detected by immunohistochemistry." (PMID 31536166, 2020). "In the present study, we aimed to investigate the mechanism of CHI3L1 in promoting proliferation and sensitivity to cetuximab in colon cancer cells." (PMID 31536166, 2020). "The results showed that the level of CHI3L1 in colon cancer tissue was significantly higher than that in adjacent tissue, which was also correlated with overall survival." (PMID 31536166, 2020). "By using the UCSC Xena platform, we demonstrated that the expression level of CHI3L1 was significantly increased in colon cancer tissues (n = 285, P < .0001)." (PMID 31536166, 2020). "We aimed to investigate the mechanism of CHI3L1 in promoting colon cancer cell proliferation and its sensitivity to cetuximab." (PMID 31536166, 2020). "Chitinase 3-like-1 (CHI3L1) is one of these factors expressed in colonic tumors, and levels of CHI3L1 mRNA are also greater in patients with active IBD." (PMID 24696788, 2012).